PROS1 (protein S)
Description:
Anticoagulant plasma protein; it is a cofactor to activated protein C in the degradation of coagulation factors Va and VIIIa. It helps to prevent coagulation and stimulating fibrinolysis.
Synonyms: PROS; PS21; PS22; PS23; PS24; PS25; PSA; THPH5; THPH6
Tractability: Antibody: its Gene Ontology location is reachable by antibodies, with high confidence; UniProt places it where antibodies can reach, with medium confidence; UniProt predicts a signal peptide or a membrane-spanning region. PROTAC: its protein half-life has been measured.
Gene: Protein-coding gene on chromosome 3 (93,873,046 to 93,980,003, reverse strand). Ensembl gene ENSG00000184500.
Subcellular location: Secreted
Pathways (Reactome):
Hemostasis: Amplification and propagation of coagulation cascade; Cell surface interactions at the vascular wall; Initiation of coagulation cascade; Platelet degranulation; Regulation of clotting cascade
Disease: Defective cleavage of FV variant at R334; Defective cleavage of FV variant at a.a.534; Dengue Virus Attachment and Entry
Metabolism of proteins: Gamma-carboxylation of protein precursors; Removal of aminoterminal propeptides from gamma-carboxylated proteins; Transport of gamma-carboxylated protein precursors from the endoplasmic reticulum to the Golgi apparatus
Immune System: Regulation of Complement cascade
Gene Ontology:
Molecular function: protein binding; calcium ion binding
Biological process: blood coagulation; negative regulation of coagulation; positive regulation of phosphatidylinositol 3-kinase/protein kinase B signal transduction
Cellular component: blood microparticle; extracellular exosome; extracellular region; endoplasmic reticulum membrane; endosome lumen; Golgi lumen; Golgi membrane; plasma membrane; platelet alpha granule lumen
Genetic constraint (gnomAD): Loss-of-function variants: 28 observed, 72.39 expected, observed/expected ratio (o/e) 0.39, 90% interval 0.29 to 0.53. The upper end of that interval is the gene's LOEUF score, 0.53, which puts it in group 2 of 6, group 1 being the genes least tolerant of losing a copy. Missense variants: 654 observed, 806.61 expected, observed/expected ratio (o/e) 0.81, 90% interval 0.76 to 0.87. Synonymous variants: 236 observed, 276.79 expected, observed/expected ratio (o/e) 0.85, 90% interval 0.77 to 0.95.
Gene-disease validity (ClinGen):
ClinGen rates the evidence that PROS1 causes each of these diseases.
protein S deficiency (semidominant): Definitive. Protein S deficiency is a disorder that causes abnormal blood clotting.
Homologues: Orthologues: chimpanzee PROS1 (99% identical), macaque PROS1 (96% identical), pig PROS1 (84% identical), rabbit PROS1 (83% identical), rat Pros1 (80% identical), guinea pig PROS1 (80% identical), mouse Pros1 (80% identical), dog PROS1 (71% identical), tropical clawed frog pros1 (58% identical), zebrafish pros1 (50% identical). Paralogues in human: SHBG (14% identical).
Diseases named in the same sentence as PROS1 in open-access papers:
PROS1 is named in the same sentence as 551 diseases in open-access papers, as found by Europe PMC text mining. Sharing a sentence is not in itself a finding about the gene and the disease. The quoted sentences say what the papers report.
thrombophilia (231 papers, 2004 to 2026). A condition characterized by an abnormally high level of thrombi. "Thrombophilia screening was conducted in 27.3% of patients, with deficiencies in protein S, protein C, and antithrombin identified in a few." (PMID 40852496, 2025). "Thrombophilia testing including the search for protein C, protein S, antithrombin deficiency, prothrombin gene (F2) G20210A and F5 Leiden G1691A mutation, and antiphospholipid antibodies was also negative." (PMID 40022289, 2025). "Of considerable significance was the number of patients newly diagnosed with thrombophilia in our cohort (30.3%), with protein S deficiency being the most common diagnosis (16.4%)." (PMID 41541846, 2025). "This is the case of a 33-year-old woman with a history of thrombophilia due to protein S deficiency type I (with decreased levels of both total and free protein S antigen) and heterozygous factor V Leiden mutation." (PMID 40981007, 2025). "This case report focuses on the challenges in the diagnosis and treatment of inherited thrombophilias with a special focus on inherited protein S deficiency." (PMID 40084314, 2025). "In this case report, we discuss the clinical course, therapeutic decisions, and implications for managing a patient with inherited thrombophilia characterized by protein S deficiency (type I) and heterozygous Factor V Leiden mutation who is diagnosed with CML." (PMID 40981007, 2025). "Hereditary thrombophilias include deficiencies of antithrombin, protein C, or protein S and gain-of-function mutations such as factor V Leiden (FVL) and prothrombin gene mutation (PGM)." (PMID 39958085, 2025). "In these cases, the identified factors associated with a hypercoagulable state included low protein S levels, prothrombin G20210A mutation, dengue viral infection, elevated anticardiolipin antibodies, and oral contraceptive use." (PMID 40177431, 2025). "Inherited thrombophilia, including protein S deficiency and Factor V Leiden mutation, poses a substantial risk for venous thromboembolism (VTE)." (PMID 40981007, 2025). "Thrombophilia screening, including tests for protein C, protein S, antithrombin III levels, factor V Leiden mutation, prothrombin G20210A mutation, and antiphospholipid antibodies, was negative." (PMID 39820409, 2025). "Thrombophilia risk factors such as low protein C level, low free protein S level, hyperhomocysteinemia (>5 μmol/L), and factor V Leiden mutation were significantly associated with RAO." (PMID 39817651, 2025). "Approximately one in seven individuals with CTEPH harbours a congenital thrombophilia, predominantly protein S or protein C deficiency, whereas factor V Leiden and prothrombin G20210A mutations are rare and ethnically restricted." (PMID 41007777, 2025). "Protein S deficiency is one of the inherited/acquired thrombophilia which results in preferential venous thromboembolism." (PMID 40084314, 2025). "A total of 835 hereditary thrombophilia tests - including those for factor V Leiden, prothrombinG20210A, deficiencies of protein S, protein C, and antithrombin, hyperhomocysteinemia, and plasminogen activator inhibitor-1 excess - were ordered in 220 patients." (PMID 41047446, 2025). "Case Presentation: A 33-year-old woman with congenital thrombophilia (type I protein S deficiency and heterozygous Factor V Leiden mutation) and a history of VTE on long-term anticoagulation with acenocoumarol presented with CML." (PMID 40981007, 2025). "In primary thrombophilia, inherited deficiencies of protein C, protein S, and antithrombin affect the hemostasis pathways related to factor V and prothrombin." (PMID 41477635, 2025). "Although the symptoms associated with acquired PS deficiency are temporary, genetic alterations in the PROS1 gene can result in pulmonary embolism, thrombophilia, venous thromboembolism and defects in development of the vascular system." (PMID 39409046, 2024).
thrombophilia (continued). "Antithrombin (AT) deficiency, protein C (PC) deficiency and protein S (PS) deficiency are the major types of hereditary thrombophilia in Japan." (PMID 38331787, 2024). "Protein S deficiency is an autosomal-inherited thrombophilia which manifests as venous or arterial thrombosis." (PMID 39409046, 2024). "This patient was found to have protein S deficiency on an outpatient hypercoagulability workup, which is most commonly diagnosed with decreased free protein S levels on assays." (PMID 39268299, 2024). "Patients with unexplained thrombosis or CVT should undergo a thorough hypercoagulability workup to identify underlying conditions like protein S deficiency, guiding treatment decisions." (PMID 39268299, 2024). "Anticoagulant protein deficiency is the most usual hereditary thrombophilia in the Chinese people, which includes protein C(PC), protein S and antithrombin deficiencies." (PMID 38504286, 2024). "Anticoagulant protein deficiency is the most usual hereditary thrombophilia in the Chinese people, which includes PC, protein S and antithrombin deficiencies." (PMID 38504286, 2024). "This study included seven cases of lower extremity deep vein thrombosis, 100 cases of hypercoagulable state, 10 cases of antiphospholipid syndrome, and eight cases of protein S deficiency, one case of hyperhomocysteinemia." (PMID 39465152, 2024). "Genetic protein S (PS) deficiency caused by PROS1 gene mutation is an important risk factor for hereditary thrombophilia." (PMID 39465133, 2024). "Among them, there were seven cases of deep vein thrombosis of lower extremities, 100 cases of hypercoagulable state, 10 cases of antiphospholipid syndrome, eight cases of protein S deficiency, and one case of hyperhomocysteinemia." (PMID 39465152, 2024). "Protein S deficiency is a form of inherited thrombophilia that occurs due to low levels of or improper function of protein S. The role of protein S is to inactivate procoagulant factors, and a deficiency results in an increased risk of thrombotic events." (PMID 37554606, 2023). "Congenital or acquired hypercoagulability is found in 20%-30% of DVTs and can be caused by genetic deficiencies of endogen protein C, protein S, and antithrombin III." (PMID 37519534, 2023). "The term “classical inherited thrombophilia” includes polymorphisms in five genes: Leiden mutations in FV gene (rs6025), the prothrombin G20210A variant (rs1799963), protein C, protein S, and antithrombin deficiencies." (PMID 36980916, 2023). "The deficiencies of antithrombin, protein C, protein S, plasminogen and dysfibrinogenemia are less common among inherited thrombophilias." (PMID 38137596, 2023). "Secondly, in a patient with patent foramen ovale (PFO) and clinically assumed paradox embolic stroke, we detected a likely pathogenic variant in PROS1, which is in the heterozygous state associated with thrombophilia due to protein S deficiency (p.Thr78Met)." (PMID 36411388, 2023). "Deficiency of certain biomarkers, such as protein C (pr C), protein S (pr S) and antithrombin (AT) can be characteristic of thrombophilia or result in acquired thrombophilia." (PMID 36295093, 2022). "Hereditary thrombophilia was detected in 8 (21.62%) patients: 5 heterozygous Factor V Leiden, 2 heterozygous F2 20210A and one protein S (PS) deficiency." (PMID 34449018, 2022). "Inherited thrombophilia is a group of disorders including factor V Leiden or Prothrombin mutation, deficiency of Antithrombin, protein C and protein S, and hyperhomocysteinemia caused by mutations in methylenetetrahydrofolate reductase." (PMID 35655618, 2022). "Three of these patients did not undergo any ATT at the time of thrombus discovery, while two of them displayed thrombophilia, including one protein S deficiency and one antiphospholipid antibody." (PMID 36348991, 2022).
thrombophilia (continued). "The most common and important hereditary thrombophilia are the Factor V Leiden, G20210A polymorphism in the prothrombin gene, deficiencies in protein C, protein S and antithrombin III, and the methylenetetrahydrofolate reductase C677T gene polymorphism." (PMID 35054824, 2022). "Evaluation for thrombophilia identified five (5%) patients with protein S deficiency, one (1%) with a factor V Leiden mutation, one (1%) with a combined protein C and S deficiency, and one (1%) with a combined factor V Leiden mutation and protein S deficiency." (PMID 35836444, 2022). "In 9/12 patients a thrombophilia screening had been performed: Protein S deficiency was found in two patients, one of whom had presented with right ventricular thrombus, and resistance to activated protein C (APC) was diagnosed in one patient." (PMID 35722497, 2022). "Thrombophilia screening studies in patients with MINOCA associated with hereditary thrombophilia include Factor V Leiden thrombophilia and protein S and C deficiency." (PMID 34540404, 2021). "Thrombophilia tests were performed in 26 patients and revealed 1 protein C deficiency, 2 protein S deficiencies, 2 heterozygotes and 1 homozygote factor V Leiden mutation and 1 prothrombin mutation." (PMID 33515066, 2021). "Those associated with severe thrombophilia are deficiency of protein C, protein S, or antithrombin III; the presence of antiphospholipid antibodies; homozygous factor V Leiden mutation; and multiple abnormalities." (PMID 33530197, 2021). "The efficacy of NOACs lacks evidence from large and randomized studies in patients with inherited severe thrombophilia, including protein S deficiency." (PMID 34273971, 2021). "Nevertheless, these studies include tests screening for inherited thrombophilia with a special focus on factor V Leiden, protein C deficiency, protein S deficiency, antithrombin III deficiency, and factor XII deficiency." (PMID 34300244, 2021). "The distribution of thrombophilic patterns in our study participants shows protein S deficiency to be the most common form of hereditary thrombophilia, while FV and protein C are the least common forms." (PMID 32351991, 2020). "Patient factors include undiagnosed thrombophilias like Protein S & Protein C deficiency, polycythemia vera, thrombocytosis and pre-operative oral contraceptive use." (PMID 31494457, 2019). "Many series report co‐existing inherited or acquired thrombophilia in 25–30% patients, especially protein S deficiency which has been associated with unusual site thrombosis in MPN patients." (PMID 30426472, 2019). "Common causes of an inherited hypercoagulable state include the following: Factor V Leiden; prothrombin gene mutations; and defects in protein S, protein C, or antithrombin." (PMID 31561622, 2019). "An increased incidence of RM has been suggested in women with inherited thrombophilia, including Factor V Leiden deficiency, activated protein C resistance, prothrombin G20210A and protein S deficiency." (PMID 31058051, 2019). "Thrombophilia due to protein C (PC) and protein S (PS) deficiencies is highly prevalent among patients with stage 5 chronic kidney disease and is reported to arise due to extracorporeal circulation during hemodialysis (HD)." (PMID 31138132, 2019). "Five inherited thrombophilias (Factor V Leiden, prothrombin gene mutation [G20210A], and protein C, protein S, and antithrombin deficiency) underlie a minority of VTE cases." (PMID 29682191, 2018). "Venous thrombosis in VZV has been suggested to be caused by autoantibodies against protein S, pre-existing hypercoagulability, or endothelial damage." (PMID 29159001, 2017). "Homozygous endothelial nitric oxid synthase (eNOS) T-786-C mutation, heterozygote prothrombin gene mutation (G-20210-A), and protein S deficiency were verified from the thrombophilia testing." (PMID 27275349, 2016).
thrombophilia (continued). "According to our previous studies, the most common heritable thrombophilias in the thromboembolic patients in Taiwan are protein S and protein C deficiencies." (PMID 27799851, 2016). "We assume that Protein S deficiency followed by preoperative bed rest and surgical invasiveness led to severe hypercoagulability and subsequent drain obstruction." (PMID 26236521, 2015). "We assume that Protein S deficiency followed by perioperative bed-rest and surgical invasiveness led to severe hypercoagulability and subsequent drain obstruction." (PMID 26236521, 2015). "Protein S deficiency is a well-known risk factor for venous thrombosis (more commonly in Asian populations than in whites), which leads to hypercoagulability and, ultimately, various types of thromboembolism." (PMID 26236521, 2015). "The cause of this thrombosis was the hypercoagulable state our patient acquired from antithrombin protein and protein S loss as part of her nephrotic range proteinuria." (PMID 26858847, 2015). "Deficiencies of the natural anti-coagulants (protein C, protein S, and antithrombin) are the predominant thrombophilias in Asia, whereas factor V Leiden and prothrombin G20210A gene mutation are rarely reported." (PMID 25047862, 2014). "In our study MTHFR (C677T) gene mutation was the most common thrombophilia factor in two groups, following by protein S deficiency." (PMID 24639756, 2013). "Cardioembolism due to dilated cardiomyopathy, atrial fibrillation, protein S deficiency, protein C deficiency, hypercoagulability, abdominal lymphomas, and disseminated Kaposi's sarcomas were common in this study as reported by other studies." (PMID 22347662, 2011). "Given the unexplained early cerebral infarction, we suspected protein S functional deficiency, since thrombophilia is a stroke risk factor in neonates and children." (PMID 21858020, 2011). "In Case 1, we postulate that PROS1 deletion-related thrombophilia predisposed to cerebral infarction, the location of which was compatible with causation of the patient's epilepsy." (PMID 21858020, 2011). "Overall, thrombophilia (antithrombin, protein C, protein S deficiency, APC-resistance, anticardiolipin antibodies) was detected in 20 patients (26%)." (PMID 22220260, 2011). "Deficiencies of natural anticoagulants protein C, protein S, antithrombin and activated protein C resistance are components of inherited thrombophilia." (PMID 21254740, 2010). "One patient had four thrombophilia markers, including raised fibrinogen, protein S deficiency, APC-R and aCL." (PMID 21181065, 2010). "In 1965 the antithrombin deficiency was described and then in the early 1980s protein C and protein S deficiencies as causes of inherited thrombophilia." (PMID 21254740, 2010). "The thrombophilia in HIV-OP is thought to be an acquired protein S deficiency with lower protein S levels and decreased activity." (PMID 20082713, 2010). "The study compared the risk for thrombosis in individuals with inherited thrombophilia due to factor V Leiden, antithrombin, protein C, or protein S deficiency." (PMID 16968541, 2006). "This was illustrated in a report which compared the risk for thrombosis in a 150 Italian individuals with inherited thrombophilia due to factor V Leiden in relation to those with antithrombin, protein C, or protein S deficiency." (PMID 16968541, 2006). "Children with congenital conditions such as protein C, protein S, or antithrombin deficiencies, as well as those with inherited thrombophilias like Factor V Leiden mutation or prothrombin gene mutations, are naturally more predisposed to developing thrombotic events." (PMID 40696594, 2025). "Thrombophilia testing: This includes evaluating for inherited conditions such as Factor V Leiden mutation, prothrombin gene mutation, and deficiencies in natural anticoagulants (antithrombin, protein C, and protein S)." (PMID 40696594, 2025).